AR (androgen receptor)
Diseases named in the same sentence as AR in open-access papers (continued):
Sharing a sentence is not in itself a finding about the gene and the disease.
prostate carcinoma (continued). "A promising small-molecule therapy approach for treating disorders connected to the androgen receptor (AR), such as prostate cancer, Kennedy’s disease, and cardiovascular conditions, is the PROTAC idea." (PMID 37241755, 2023). "It is reported that MAGEB2 binding to androgen receptor promotes prostate cancer proliferation through upregulation of PSA and NX3.1." (PMID 37304127, 2023). "Specifically, silymarin, silibinin, silybin A (1A), and silybin B (1B) have been reported to reduce the secretion of prostate-specific antigens in AR-positive LNCaP prostate cancer cells." (PMID 37111288, 2023). "AR mediated androgen signaling is pivotal in prostatic malignancies, hence much of our knowledge on the mechanistic basis of AR signaling is derived from prostate cancer (PCa) studies." (PMID 36720985, 2023). "Resistance to androgen receptor signalling inhibitors (ARSIs) represents a major clinical challenge in prostate cancer." (PMID 37673961, 2023). "Second, the impact of MLL5α on activation of AR/NDRG1 signaling has been found to result in the suppression of prostate cancer progression." (PMID 37249826, 2023). "PARP1 activity is significantly increased in CRPC cells compared to that in hormone-sensitive prostate cancer cells, and PARP inhibitors cause the depletion of both the androgen receptor (AR) and PARP1 on DNA in CRPC cells in vitro and in vivo." (PMID 37174127, 2023). "Androgen and estrogen receptors have been shown to intersect with the HIF/NF-kB signaling in prostate cancer, and hypoxia increases androgen receptor activity within a low-androgen environment." (PMID 37384143, 2023). "In contrast, PSA serves as a diagnostic and surrogate endpoint marker for pharmacological strategies against AR activation in prostate cancer." (PMID 36765659, 2023). "For example, the androgen receptor (AR) plays a crucial role in the pathogenesis of prostate cancer and is late in treatment due to the adaptation of PCa cells to low levels of androgens." (PMID 38117350, 2023). "The abnormally activated androgen receptor (AR) activity is the main driving factor of resistant prostate cancer (CRPC)." (PMID 37049787, 2023). "Consistent with previous reports, biopsies with high metabolic activity showed activated AR and glucocorticoid receptor signaling but suppressed neuroendocrine prostate cancer signature." (PMID 38099500, 2023). "In prostate cancer, the interaction between AR activity and the signaling pathways it regulates, such as the PI3K and RAS pathways, is well known." (PMID 38067367, 2023). "In contrast, CCN3 can suppress enzalutamide-resistant prostate cancer cell proliferation by inhibiting androgen receptor signaling in prostate cancer cells." (PMID 37373471, 2023). "Through various AR-related mechanisms, prostate cancer eventually escapes ADT and progresses toward castration resistance." (PMID 37509723, 2023). "AR antagonists are effective for the treatment of mCRPC, significantly improves the survival of prostate cancer patients with well tolerance." (PMID 37261210, 2023). "These demonstrated that the inhibitors kaempferol and apigenin were well-suited to the active site of the androgen receptor Prostate Cancer (2Q7L) and interacted with the residues essential for their biological activities." (PMID 36679271, 2023). "The knowledge gained from this study indicates that WBM intake affects prostate cancer by interfering with the AR signaling axis." (PMID 36765659, 2023). "We found an inhibitory effect of pinostilbene on nuclear localization of AR and confirmed cytotoxicity and growth inhibition effects on prostate cancer cell lines." (PMID 37794090, 2023). "The downregulation of AR is required for the maintenance of self-renewal capabilities in stem cells of prostate cancer." (PMID 37314603, 2023). "Androgen is an important physiological medium to promote the progress of prostate cancer by activating androgen receptor (AR)." (PMID 36823643, 2023).
prostate carcinoma (continued). "It is supposed that the dynamic changes of the AR gene meet the needs of prostate cancer evolution, and the continuous progression of prostate cancer also provides the motivation for AR remodeling." (PMID 37190171, 2023). "The optimized compounds had more affinity for their target, inhibited androgen-receptor-dependent transcriptional programs, and had an antitumorigenic effect in models of castration-resistant prostate cancer in cells and in vivo." (PMID 38049566, 2023). "GRP78 interacts with and stabilizes the androgen receptor, which is crucial for prostate cancer growth and progression." (PMID 37605113, 2023). "In prostate cancer, androgen receptors synergistically regulate the expression of ACSL3 and ACSL4, and knocking out ACSL4 inhibits the proliferation, migration, invasion, and xenograft growth of androgen receptor dependent prostate cancer cells." (PMID 37305043, 2023). "LNCaP is an androgen-sensitive cell line that represents the androgen-sensitive prostate cancer, and abl is its androgen-refractory counterpart, which are AR-positive and represent most of the CRPC." (PMID 36614243, 2023). "In this setting, targeting the androgen receptor (AR) signaling axis, whose activation is mediated by androgens, is the key to controlling prostate cancer progression." (PMID 37189723, 2023). "Further investigation of this is clearly warranted, given the importance of the androgen receptor in prostate cancer progression and treatment, and that SNHG1 levels dramatically affect quiescence and cell cycle as we have shown here." (PMID 37464317, 2023). "For instance, KDM8 / JMJD5, a histone lysine demethylase/dioxygenase, directly targets ATAD2 to maintain cell survival via AR activation of EZH2 in prostate cancer." (PMID 36632213, 2023). "In prostate cancer, the therapeutic potential of AhR ligands has been studied primarily in the context of androgen receptor (AR) suppression and the anti-androgenic effects." (PMID 37241719, 2023). "In cellular models of castration-resistant prostate cancer (CRPC), ARCC-4 was more effective at inducing apoptosis and inhibiting proliferation of AR-amplified prostate cancer cells compared to its parent compound, enzalutamide." (PMID 37175108, 2023). "Androgen receptor targeting remains the primary therapeutic strategy in prostate cancer, encompassing androgen biosynthesis inhibitors and androgen receptor antagonists." (PMID 37894395, 2023). "Both ligand-dependent and ligand-independent activation are extremely important for the AR, and suppression of the receptor activity has become one common prostate cancer therapy." (PMID 37998041, 2023). "Several lncRNAs have been shown to contribute to the pathogenesis of prostate cancer via modulation of AR signaling, ubiquitin–proteasome degradation process of AR or other important signaling pathways." (PMID 37025585, 2023). "The lncRNA PCAT1 in prostate cancer upregulates androgen-responsive gene levels through the recruitment of androgen receptor and lysine-specific demethylase 1, leading to the growth and proliferation of prostate cancer cells." (PMID 36936418, 2023). "We have been working on optimizing silibinin to improve its potency and selectivity toward AR-positive prostate cancer cells." (PMID 37111288, 2023). "Androgen receptor targeted therapies for prostate cancer have serious limitations in advanced stages of the disease." (PMID 36300876, 2023). "The ROS level increased regarded as an important process in the newly discovered ferroptosis pathway, and androgen receptor antagonists can induce ferroptosis in prostate cancer cells during androgen depletion therapy for prostate cancer patients." (PMID 37547873, 2023). "An antisense oligonucleotide designed to target an ISE of the AR pre-mRNA can shift the isoform balance toward full-length androgen receptor proteins in prostate cancer cells and can re-sensitize cells to androgen depletion." (PMID 36979496, 2023).
prostate carcinoma (continued). "The de-repression of AR target genes upon treatment with a pan-HDAC inhibitor was much more significant in ERG-positive prostate cancer cells than ERG-negative prostate cancer cells." (PMID 37735473, 2023). "Here, we report that the leucine carboxy methyltransferase (LCMT1), which methylates the L309 residue of the C subunit, acts as a suppressor of androgen receptor (AR) addicted prostate cancer (PCa)." (PMID 37644036, 2023). "Since prostate cancer (PCa) was described as androgen-dependent, the androgen receptor (AR) has become the mainstay of its systemic treatment: androgen deprivation therapy (ADT)." (PMID 37189723, 2023). "In recent years, the FDA has approved three new competitive AR antagonists for the treatment of prostate cancer." (PMID 36768610, 2023). "In particular, FEN1 overexpression reversed apoptosis and cell cycle arrest in prostate cancer cells due to the synergistic effects of AR knockdown and DTX." (PMID 37326412, 2023). "New therapies directed against the AR and AR signaling have shown a clear survival benefit in patients with prostate cancer." (PMID 37175938, 2023). "Additional studies on prostate cancer have demonstrated that the m6A-modified androgen receptor (AR) mRNA phase separated with YTHDF3, while the unmodified AR mRNA phase separated with G3BP1 to survive AR pathway inhibition stress." (PMID 38110976, 2023). "Most early-stage prostate cancers are androgen-dependent and so the AR is critical in driving the development of prostate cancer." (PMID 37830741, 2023). "PHB overexpression leads to G1/S-phase cell cycle arrest, and PHB represses the androgen receptor (AR) in prostate cancer cells." (PMID 37373067, 2023). "This was confirmed in another study which documented how INPP4B impacts the AR transcriptional program and that its depletion stimulates prostate cancer cell proliferation." (PMID 36768610, 2023). "The antitumor specificity of ITRI-90 via AR targeting was further validated by its ineffectiveness towards AR-negative PC3 prostate cancer model." (PMID 36893587, 2023). "CDK4/6 inhibitors have been used in advanced prostate cancer to disrupt such AR signalling pathways and prevent cell proliferation." (PMID 36029329, 2023). "Through gene mutation and amplification, prostate cancer cells are able to develop resistance to ADT treatment by restoring AR signaling, ultimately yielding castration-resistant prostate cancers (CRPC)." (PMID 37834162, 2023). "Collectively, these indicate AR pathway suppression as a secondary mode of action of CT7001 in prostate cancer cells, in addition to cell cycle inhibition." (PMID 37076563, 2023). "Although several chemokines are capable of recruiting TAMs to the TME, the chemoattractant C-C motif ligand 2 (CCL2), alias MCP1, is the key factor and is known to be induced in prostate cancer in response to AR inhibition." (PMID 36672395, 2023). "Differences in AR cistromes have been reported between early and late-stage prostate cancer samples." (PMID 36768610, 2023). "Prostate cancer is a hormone-dependent cancer that relies on androgens acting via binding to its receptor, androgen receptor (AR)." (PMID 36711033, 2023). "Androgen receptor (AR) pathway modulation represents a key therapeutic approach for patients with prostate cancer (PCa)." (PMID 37902861, 2023). "In the context of prostate cancer, AR has been found to stimulate the expression of TFEB, thereby promoting autophagy induction." (PMID 37834333, 2023). "Understanding the regulatory mechanisms of AR has important clinical implications for this most aggressive type of prostate cancer." (PMID 37142586, 2023). "In such studies, we also have introduced enzalutamide, an USFDA-approved synthetic AR antagonist for prostate cancer, as the reference drug." (PMID 36765659, 2023). "Both enzalutamide and abiraterone have shown good results as AR antagonists in the treatment of prostate cancer." (PMID 36733714, 2023).
prostate carcinoma (continued). "The clinically used androgen receptor (AR) antagonistsfor thetreatment of prostate cancer (PCa) are all targeting the AR ligandbinding pocket (LBP), resulting in various drug-resistant problems.Therefore, a new strategy to combat PCa is urgently needed." (PMID 37122451, 2023). "Eventually prostate cancer cells overcome androgen deprivation therapy, giving rise to castration resistant prostate cancer (CRPC) characterized by increased androgen receptor (AR) activity." (PMID 36809527, 2023). "For example, in prostate cancer, AR can negatively regulate the expression of β-catenin by enhancing miR-4496 expression through direct binding to the AREs in the promoter of miR-449640." (PMID 37496996, 2023). "AR-signaling axis is crucial in all stages of prostate cancer, and the involvement of AR in CRPC progression has been observed for a long time." (PMID 37729607, 2023). "The progression of prostate cancer is driven by the androgen receptor (AR) and first line treatments for advanced prostate cancer include AR-targeted therapies." (PMID 37813880, 2023). "Collectively, our studies demonstrate that AR knockdown improves the DTX sensitivity of prostate cancer cells by downregulating FEN1 through the ERK/ELK1 signalling pathway." (PMID 37326412, 2023). "The androgen receptor (AR) is a ligand-dependent nuclear receptor that plays a critical role in prostate cancer initiation and progression." (PMID 37076563, 2023). "AR blockade not only synergizes with DTX in prostate cancer, clinical studies have also shown that abiraterone combined with olaparib therapy has achieved satisfactory results in mCRPC patients." (PMID 37326412, 2023). "To further establish the feasibility and relevance of using plasma-derived EVs to monitor expression of GR and ENZA resistance, we studied a PDX MDA prostate cancer (PCa) 322-2-6a that is AR+/GR−." (PMID 37930121, 2023). "The molecular crosstalk between ERG and androgen receptor (AR) has implications in the complex network of prostate cancer signaling pathways." (PMID 37310937, 2023). "In recent years, as the mechanisms of androgen activity in prostate cancer have been studied, we have gained a richer understanding of the immune regulatory mechanisms played by androgens and AR in patients with prostate cancer." (PMID 36925917, 2023). "Great attention is paid to the role of androgen receptor (AR) as a central transcriptional factor in driving the growth of prostate cancer (PCa) epithelial cells." (PMID 37092583, 2023). "Compound ARV‐110 is an AR degrader drug discovered by Crews group and Arvinas, Inc. to overcome the developed drug resistance of prostate cancer." (PMID 37261210, 2023). "We have previously reported that the compound A4B17 derived from a screen of 47 benzothiazoles inhibited proliferation of ER+ breast and AR+ prostate cancer cells with half maximal inhibitory concentrations (IC50) in the micromolar range." (PMID 37520743, 2023). "AKR1C3 promotes tumor growth in prostate cancer cells by increasing androgen production or activating AR-mediated signaling." (PMID 38188684, 2023). "TMPRSS2 is a well-known transcriptional target of AR in prostate cancer cells and has recently shown to be regulated by androgens and anti-androgens also in lung cells and mouse lung tissue." (PMID 37287057, 2023). "To identify co-amplified genes, in a cohort of 492 primary prostate cancer tumors, we found that AR resided in a focal amplicon on Xq12 with 9 additional genes based on GISTIC 2.0 outputs." (PMID 37059746, 2023). "A recent study revealed that the NRP2B transcript variant reduces the transcriptional activity of the AR in advanced prostate cancer by altering AR binding to the regulatory regions of AR target genes." (PMID 37600714, 2023). "It is also shown to epigenetically upregulate the expression of the AR gene in prostate cancer cells." (PMID 36959798, 2023).
prostate carcinoma (continued). "Au-AR pep PROTAC fully inhibits the development of AR-positive prostate cancer cells at high concentrations (above 500 nM)." (PMID 37631305, 2023). "Enzalutamide is widely used in the treatment of prostate cancer by targeting the ligand binding domain of AR and inhibiting the activity of AR." (PMID 36823643, 2023). "Prostate cancer progression requires AR, which highly depends on HSF1-activated multichaperone complexes such as HSP70 and HSP40." (PMID 37958341, 2023). "Taken together, altering glucuronidation is another mechanism by which ADRB2 can regulate the AR in prostate cancer cells." (PMID 37830741, 2023). "The androgen receptor (AR) signaling pathway plays a pivotal role in prostate development and homeostasis, as well as in the progression of prostate cancer." (PMID 37476073, 2023). "The androgen receptor (AR)-regulated transcriptional pathway provides the main impetus to prostate cancer cell growth and metathesis." (PMID 37444418, 2023). "In previous studies, AR was reported to transduce hormonal signals to regulates multiple prostate cancer events, proliferation, apoptosis, migration, invasion, and differentiation." (PMID 36744249, 2023). "Resveratrol (3,4′,5-trans-trihydroxystilbene), a precursor to pinostilbene (3,4′-dihydroxy-5-methoxystilbene), has been shown to have anticancer activity against prostate cancer and to inhibit transcription activity of AR as well as its protein expression." (PMID 37794090, 2023). "The crosstalk between β-catenin and AR often leads to a progression of prostate carcinomas, due to altered gene expression." (PMID 38348349, 2023). "The androgen receptor (AR) transcriptional signal pathway activated by androgen is the driving force for the development and progression of prostate cancer." (PMID 37375297, 2023). "Over 90% of prostate cancer (PCa) are diagnosed as luminal adenocarcinoma featured with abnormal AR expression and activity." (PMID 37385990, 2023). "The androgen-sensitive, endogenous AR-expressing LNCaP prostate cancer cell line is the model originally and most widely used to describe prostate cancer cell lipid metabolism." (PMID 37874216, 2023). "The semi-synthetic 3rd generation taxane derivative cabazitaxel was able to inhibit LNCaP and PC-3 prostate cancer cell proliferation and suppress Hsp40, HOP, and AR in prostate cancer cells at very low doses (0.3 nM)." (PMID 36835501, 2023). "MI-136 treatment blocked the AR signaling pathway of prostate cancer cell lines (LNCaP and VCaP) in mice and restricted the proliferation of castration-resistant tumors." (PMID 37049787, 2023). "These drug-resistance mechanisms confound treatment of this ‘castration resistant’ stage of prostate cancer, characterised by the return of AR signalling." (PMID 36674785, 2023). "The interaction between AR and α-tubulin was detected in two AR-positive prostate cancer cell lines (LNCaP and CWR22) by yellow immunofluorescence staining." (PMID 37444418, 2023). "Prostate cancer initiation and progression are dependent on androgen receptor (AR) signaling, which changes from promoting differentiation to stimulating proliferation and metastasis." (PMID 38001678, 2023). "The Androgen Receptor (AR) is critical for the development of prostate cancer (PC) and remains a critical target in both metastatic prostate cancer (mPC) and metastatic castration-resistant prostate cancer (mCRPC)." (PMID 37059746, 2023). "Androgen receptor (AR) plays a vital role in prostate cancer (PCa), including castration-resistant PCa, by retaining AR signalling." (PMID 36203075, 2023). "Compounds inhibited the growth of five prostate cancer cell lines, with many exhibiting differential cytotoxicity towards AR positive cell lines." (PMID 37549772, 2023). "It is a coactivator both of MYC and AR and contributes to the reprogramming of the androgen network and central metabolism in prostate cancer cells." (PMID 37443779, 2023).